BRAF (B-Raf proto-oncogene, serine/threonine kinase)
Diseases named in the same sentence as BRAF in open-access papers (continued):
Sharing a sentence is not in itself a finding about the gene and the disease.
melanoma (continued). "In all, these studies represent promising steps forward for the use of pan-RAF inhibitors on not only BRAFV600E but also BRAF-wild type and CRAF-wild type melanoma patients." (PMID 38732242, 2024). "In our study, we explored the potential role of LOXL3, SNAI1, and NES in melanoma progression and metastasis among patients with dysplastic nevi, melanoma in situ, and BRAF+ and BRAF− metastatic melanoma, using immunofluorescence and qPCR analysis." (PMID 39273022, 2024). "Research has shown that the combination of dabrafenib and trametinib demonstrates meaningful efficacy in various BRAF-positive tumor types, such as NSCLC, melanoma, and ATC, and among patients with some rare cancers that lack other treatment options." (PMID 39529955, 2024). "So far, studies carried out in tumour biopsies and cfDNA have reported that alterations in MAPK pathway are predominant both in melanoma and NSCLC at BRAF-targeted therapy failure." (PMID 38177660, 2024). "Another study demonstrates that the combination of a BRAF inhibitor and MEK inhibitor activates caspase-3 GSDME-mediated pyroptosis in melanoma, leading to increased immune response and tumor suppression in melanoma-bearing mice." (PMID 38799433, 2024). "Multiple studies found that the first combined BRAF and MEK inhibitors therapy showed significant improvement in an investigator-assessed overall response and relapse-free survival in treating melanoma, which led to global approval." (PMID 39776585, 2024). "It is important to note that the A375 melanoma cell line is homozygous for BRAFV600E, so all transposon insertion events impact expression of the oncogenic form of BRAF." (PMID 38213996, 2024). "Next, we screened the supernatant of BRAF/MEK-inhibited and control melanoma cells 24 h after 3pRNA stimulation for cytokine expression." (PMID 39165562, 2024). "For example, the prevalence of BRAF mutations, which promote tumor growth and angiogenesis alone, is not an indicator of treatment success; the BRAF inhibitor vemurafenib was effective in treating melanoma but not colorectal cancer, despite both having a high frequency of BRAF mutations." (PMID 39017990, 2024). "A phase II C-144-01 trial evaluated the safety and the efficacy of lifileucel in patients with advanced melanoma who had progressed on ICI and BRAF inhibitors." (PMID 39727691, 2024). "More recent studies have examined the role of PAX3 in early drug tolerance to BRAF and MEK inhibitors in melanoma." (PMID 38473380, 2024). "The results obtained for apoptosis induction on another melanoma cell line SK-MEL-2, expressing mutant N-Ras (Q61R) and wildtype BRAF showed a similar trend to the one observed for SK-MEL-28." (PMID 39684214, 2024). "Although a number of important scientific milestones have been achieved in the fight against melanoma, the FDA approval of BRAF V600E and MEK inhibitors for example, the 5-year survival rate of metastatic individuals remains poor." (PMID 38775844, 2024). "While BRAF and MEK inhibitors can be effective in melanoma patients, resistance to these therapies often develops." (PMID 39436655, 2024). "BRAF can activate the MEK signal transduction pathway through the phosphorylation and activation of MEK to promote the proliferation of melanoma cells and inhibit their apoptosis." (PMID 38335433, 2024). "We conducted a study comparing the utilization of modern immunotherapy relative to targeted BRAF/MEK inhibitors/chemotherapy in stage III and IV melanoma cases and evaluated factors influencing the timing of immunotherapy administration." (PMID 38186321, 2024). "Immunotherapy with immune checkpoint inhibitors and targeted therapy with BRAF and MEK inhibition have revolutionized the treatment of melanoma." (PMID 38365756, 2024). "As a transcription factor, POU4F1 has been shown to transcribe and regulate the expression of MEK in melanoma, thereby reactivating the MAPK pathway and leading to resistance against BRAF inhibitors." (PMID 38962013, 2024).
melanoma (continued). "The expression levels of the FER1L4 in normal melanocytes - HEMa and HEMn (BRAF WT) cell lines, and human melanoma cell lines MEWO (BRAF WT), SKMEL28, WM9, A375 (BRAF V600E), WM115, and WM266 (BRAF V600D) were measured using qRT-PCR." (PMID 39764216, 2024). "Upon transfer to recipient melanoma cells, PDGFRβ triggers a dose-dependent activation of the PI3K/AKT signaling pathway, enabling these cells to circumvent BRAF inhibition." (PMID 39403600, 2024). "In melanoma, CDK4/6 inhibitors, especially the oral inhibitor palbociclib, have been applied in combination with other inhibitors, which are targeted at BRAF and MEK." (PMID 39598629, 2024). "All the clinically relevant targets such as BRAF and NRAS have a comparable distribution thus suggesting the value of larger scale sequencing in melanoma." (PMID 38184610, 2024). "MEK inhibitors, which target elements downstream of BRAF in the MAPK signaling pathway, are an important therapeutic option for melanoma treatment." (PMID 38474231, 2024). "Here, this comprehensive review will cover the developments of BRAF and MEK inhibitors from melanomas to tumor-agnostic indications, novel drugs, challenges, future directions, and the importance of those drugs in personalized medicine." (PMID 38203795, 2024). "Immunotherapy with immune checkpoint inhibitors and targeted therapy with BRAF and MEK inhibition have transformed the treatment of melanoma." (PMID 38365756, 2024). "In recent years, targeted therapy with BRAF/MEK inhibitors and immunotherapy with PD-1, PD-L1, and CTLA-4 inhibitors have made significant strides in the outcomes and prognosis of melanoma." (PMID 39749047, 2024). "Previous work has shown that encorafenib monotherapy is sufficient to downregulate the RAS/BRAF/MAPK signaling pathway and strongly decreases cancer cell viability in BRAF mutant melanoma tumors." (PMID 39018564, 2024). "Trials with triplet regimes of BRAF- and MEK-inhibitors in combination with immunotherapy with immune checkpoint inhibitors have shown not only a more durable response in melanomas but also more adverse events." (PMID 38716076, 2024). "The advent of immune checkpoint inhibitors and combination therapy with BRAF inhibitors and MEK inhibitors has dramatically improved the prognosis of advanced melanoma." (PMID 38087810, 2024). "A crucial role of molecularly targeted agents inducing selective BRAF inhibition and, thus, inhibiting the abnormal MERK signaling pathway in melanoma is to restore apoptosis." (PMID 38254853, 2024). "Analysis of the BRAF, NRAS, and NF1 genes in patient samples will allow for the classification of melanoma into four proposed molecular subtypes." (PMID 39340537, 2024). "Here we used whole genome sequencing to genetically characterize the triple-wild-type melanoma (TWM), termed here as BRAF, RAS and KIT wild type, using the most common histological forms and excluding rare ones." (PMID 36980598, 2023). "Of the patients with melanoma, 125 (61.9%) were treatment‐naïve, 78 (38.6%) had an elevated LDH at commencement of immunotherapy, 39 (19.3%) were BRAF V600E positive, 150 (74.3%) were Stage VI M1C/D by the AJCC Melanoma Staging 8th Edition." (PMID 36404632, 2023). "Combination of inhibitors for BRAF and MEK in MAPK pathway has become a standard front‐line therapy for BRAF‐mutant melanoma." (PMID 37016119, 2023). "SSM: Superficial spreading melanoma; ALM: Acral lentiginous melanoma; NM: Nodular melanoma; LMM: Lentigo maligna melanoma; TILs: Tumor-infiltrating lymphocytes; BRAF: v-raf murine sarcoma viral oncogene homolog B." (PMID 37649946, 2023).
melanoma (continued). "Similarly, as suggested previously, an alternative hypothesis could be that the biology of melanoma is similar to that of other cancers where biology drives mutual exclusivity, for example activation of the MAPK pathway via either BRAF or NRAS mutation, but chance explains most co‐occurrences." (PMID 36219477, 2023). "In melanoma 25, TSLNC8 overexpression sensitized cells to the BRAF inhibitor PLX4720, promoting apoptosis and reducing colony formation." (PMID 37781073, 2023). "These medications specifically target BRAF kinase, disrupting the functioning of the MAPK signaling pathway, which plays a pivotal role in regulating the growth and viability of melanoma cells." (PMID 38021761, 2023). "A significant regulator of melanoma cell invasion and a possible target for melanoma treatment and prevention is the MAPK (BRAF-MEK-ERK) pathway." (PMID 37565061, 2023). "Given the significance of BRAF activation in melanoma cells, the down-regulation of both BRAFWT (D24 melanoma cells) and BRAFV600E (MM418-C1) in the water seed extract treated cells assumes importance." (PMID 36678596, 2023). "Evaluating the safety of combing BRAF and MEK inhibitor therapy with melanoma helper peptides (6MHP) administration assesses the impact on the immune system." (PMID 38105263, 2023). "Dabrafenib, encorafenib, and vemurafenib are FDA-approved small molecule inhibitors of BRAF and are frequently used in combination with MEK inhibitors to treat BRAF-mutant melanoma patients." (PMID 37857607, 2023). "Genomic alterations of BRAF and NRAS are oncogenic drivers in malignant melanoma and other solid tumors." (PMID 37219686, 2023). "By halting BRAF activity, they disrupt the MAPK signaling pathway responsible for governing melanoma cell proliferation and survival." (PMID 38021761, 2023). "In Asian patients with advanced BRAF V600‐mutant melanoma, the superiority of first‐line PD‐1/CTLA‐4 over BRAF/MEKi appears modest." (PMID 37584204, 2023). "Clinical management of melanoma LMD consists primarily of radiation therapy, BRAF/MEK inhibitors as targeted therapy, and immunotherapy with anti-PD-1, anti-CTLA-4, and anti-LAG-3 immune checkpoint inhibitors." (PMID 36980770, 2023). "However, in the CheckMate 067 study it was demonstrated that the 5 year overall survival rate was 60% for BRAF mutant melanoma patients with combined ipilimumab and nivolumab therapy compared to 48% in BRAF wildtype patients, indicating a positive predictive value for BRAF mutant melanoma." (PMID 35192052, 2023). "Particularly in 2011, vemurafenib became the first BRAF-targeted therapy approved by the Food and Drug Administration (FDA) for the treatment of melanoma." (PMID 37993971, 2023). "Vemurafenib is a specific mutant BRAF inhibitor; consistently, in the in vitro models used here, the SK-MEL-28 cell line and primary melanoma cells (both harboring BRAFV600) were sensitive to this drug, reaching an IC50 lower than 1 μM." (PMID 37189846, 2023). "While BRAF and MEK inhibitors have revolutionized the treatment of melanoma patients resistance frequently occurs after several months of treatment." (PMID 36678596, 2023). "Our data now provide the first evidence that the whole PLK1 pathway is strongly downregulated after the inhibition of BRAF and EZH2 in resistant melanoma cells." (PMID 36768289, 2023). "This prompted testing of vertical dual inhibition of MAPK pathway with BRAF and MEK inhibitors, an approach that has improved response rates in melanoma." (PMID 37920169, 2023). "Based on this study, it has shown activities for various BRAF V600E or KRAS mutant cancers, including melanoma and colorectal cancer in vitro and in vivo." (PMID 36872366, 2023). "We also studied the effect of CINN-EO in combination with other two conventional drugs used in melanoma therapeutics, the antimitotic paclitaxel (PTX) and the BRAF inhibitor dabrafenib (DAB), on melanoma cell survival." (PMID 36982774, 2023).
melanoma (continued). "BRAF inhibitors improve the TME and anti-tumor immune response in BRAF-mutant melanoma because the MAPK pathway activates the T-cell receptor." (PMID 38001644, 2023). "The combination of ipilimumab and nivolumab and the combination of BRAF and MEK inhibitors have improved survival of patients and are current standards for combination therapies in immunotherapy and targeted therapy of melanoma." (PMID 37507765, 2023). "Studies focusing on melanoma have shown that B-cell infiltration in the TME results in the secretion of insulin-like growth factor 1 (IGF1), which promotes drug resistance to BRAF and MEK inhibitors." (PMID 36945046, 2023). "BRAF p.K601N has been reported in rare cases of FTC, thyroid lymphoma, lung carcinoma, colorectal carcinomas, and melanoma." (PMID 36835466, 2023). "Its activity was demonstrated in BRAF-mutant, NRAS-mutant, and WT melanoma cell lines, as well as in xenograft melanoma models." (PMID 36902392, 2023). "(ρ = 0.524) In a next step we analyzed the TCGA (melanoma) and GTEx (healthy skin) databases for potential alterations of gene expression of MALAT1 in relation to NRAS, BRAF, MEK1, MEK2, ERK1 and ERK2 gene expression." (PMID 37235843, 2023). "As theBRAF V600Emutation has also been described in melanomas and the treatment with MEK and BRAF inhibitors has drastically changed the evolution of that disease, MEK and BRAF inhibitors have also been considered for treatment of selected PCPs." (PMID 36748936, 2023). "Although both BRAF-mutant and NRAS-mutant melanomas have activation of the MEK/ERK pathway, MEK inhibitors (MEKi) are only effective for the BRAF-mutant subtype." (PMID 36765910, 2023). "In the case of melanoma, the constitutively active MAPK pathway is targeted by a combinatorial inhibition of BRAF and MEK activities." (PMID 37325027, 2023). "Treatment of colorectal and thyroid cancers with BRAF inhibitors leads to excessive activation of RAS and rapid rebound of ERK signaling, which is more pronounced than that observed in melanoma." (PMID 37325052, 2023). "We found that combined treatment with inhibitors against BRAF and EZH2 indeed showed synergistic effects against cancer cells and improved the response of melanoma cells resistant to vemurafenib." (PMID 36768289, 2023). "Since receptor-interacting protein kinase (RIPK4) probably functions as an oncogene in melanoma and its structure is similar to the BRAF protein, we analyzed the impact of vemurafenib and dabrafenib on RIPK4 in melanomas." (PMID 36765875, 2023). "BRAF and MEK are both kinases that are involved in regulating the proliferation and growth of melanoma cells via the mitogen-activated protein kinase/extracellular signal-related kinase (MAPK/ERK) pathway." (PMID 37444454, 2023). "Notably, the sorafenib/trametinib combination has already been applied in the context of BRAF class III mutations and advanced hepatocellular carcinoma, while first clinical data on naporafenib/trametinib combinations have recently been published for NRAS-driven melanoma." (PMID 37656784, 2023). "Small-molecule BRAF and MEK1/2 inhibitors (RAFi and MEKi) are now approved and used in the clinic to treat BRAF-mutant melanoma and BRAF-mutant colorectal cancer." (PMID 37018014, 2023). "In melanoma cells, ITCH-mediated BRAF ubiquitination is pivotal in coordinating the signals between cytokines and MAPK pathway activation." (PMID 37760946, 2023). "Several therapeutic strategies currently used in the treatment of melanoma and the combination of BRAF and MEK-inhibitors, as well as immune check-point inhibitors (ICI), have consistently improved the overall survival time of melanoma patients." (PMID 36831417, 2023). "As shown here, the BRAF inhibitor vemurafenib and the ERK inhibitor SCH772984 showed only limited efficacy in melanoma cell lines, when applied alone." (PMID 36902392, 2023).
melanoma (continued). "Several BRAF and MEK inhibitors have been approved for treatment of these melanomas, such as vemurafenib, dabrafenib, encorafernib, trametinib, binimetinib, selumetinib and cobimetinib." (PMID 36678596, 2023). "Only one BRAF V600+ patient (#39), whose melanoma harbored both BRAF amplification and PTEN deletion, responded to BRAF+MEKi." (PMID 36901733, 2023). "For example, combining the BRAF inhibitor dabrafenib and the MEK inhibitor trametinib leads to long-term clinical benefits in patients with melanoma." (PMID 37830744, 2023). "Targeted therapy with BRAF and MEK inhibitors (BRAFi, MEKi) is one of the mainstays of melanoma treatment." (PMID 36900217, 2023). "With the utilization of three categories of anti-cancer drugs, namely BRAF-targeted, MEK-targeted, and Immune checkpoint inhibitors (ICIs) on melanoma, significantly improved OS had been achieved in advanced-stage patients." (PMID 37770477, 2023). "The adaptive acquisition of resistance to BRAF and MEK inhibitor-based therapy is a common feature of melanoma cells and contributes to poor patient treatment outcomes." (PMID 37176114, 2023). "We previously provided evidence that the HDAC inhibitor ITF2357 (Givinostat) targets oncogenic BRAF in SK-MEL-28 and A375 melanoma cells." (PMID 37298104, 2023). "BRAF inhibitors alone or in combination with MEK inhibitors, for example, significantly boosted OS and PFS in melanoma patients." (PMID 37745303, 2023). "The rationale for developing targeted inhibitors of mutant BRAF and MEK, the kinase that functions downstream of BRAF to activate ERK, as treatments for advanced melanoma was supplied by these findings." (PMID 37569598, 2023). "The reduction of HAT1 expression in metastatic melanoma caused the development of the v-raf murine sarcoma viral oncogene homolog B1 (BRAF) inhibitors’ resistance, such as vemurafenib and dabrafenib, kinase inhibitors targeting BRAFV600E in melanoma cells." (PMID 37048148, 2023). "Mutations in the kinase domain of BRAF, specifically found at the V600 site, are frequently found to be drivers of cancer, including a prevalence of mutations noted in, but not exclusive to, melanoma, colorectal cancer, non‐small cell lung cancer and differentiated thyroid cancer." (PMID 37775918, 2023). "Combined BRAF and MEK inhibition is now the standard of care in melanoma, non-small cell lung cancer, and anaplastic thyroid cancer." (PMID 37231247, 2023). "In agreement, chronic treated BRAF-inhibitor resistant A375P, K029A, and SKMEL3 melanoma cells exhibited reduced expression of these two RAB genes." (PMID 37277330, 2023). "The prognostic significance of BRAF mutations has been widely controversial as some studies have found that BRAF-mutated melanomas may be associated with worse survival and higher risk of recurrence but other studies have shown no survival difference compared to BRAF wild-type." (PMID 37900283, 2023). "Inhibition of BRAF, as well as downstream MEK, suppresses this driver mechanism in melanoma proliferation." (PMID 37513847, 2023). "We found that several IL-17-inducing genes were expressed at higher levels in BRAF-mutant than in BRAF-WT tumors in the SKCM cohort and that their expression was significantly decreased in MAPK inhibitor (MAPKi)-treated melanoma tissue biopsies." (PMID 37525015, 2023). "Currently, a selective mutant BRAF/MEK inhibitor combination with immunotherapy shows a very good response (about 75%) and is largely used in the treatment of BRAF mutant melanoma patients." (PMID 37215708, 2023). "Since TYR, TYRP1, TYRP2, PMEL, and MELAN-A are recognised as melanocyte differentiation antigens (MDAs), inhibition of BRAF V600E increases MDAs expression, through the upregulation of MITF, enhancing melanoma immunogenicity." (PMID 37627054, 2023). "It has been revealed that the mutant oncogene BRAF can control the expression of MITF, ensuring that levels of protein are suitable for the growth and survival of melanoma cells." (PMID 37102943, 2023).